CTLA4 (cytotoxic T-lymphocyte associated protein 4)
Diseases named in the same sentence as CTLA4 in open-access papers (continued):
Sharing a sentence is not in itself a finding about the gene and the disease.
Autoimmunity (continued). "Using this model, they successfully showed that risk variants of autoimmunity were enriched in cell-state-dependent eQTLs (e.g., ORMDL3 and CTLA4 loci), indicating that cell-state context is crucial to understanding the genetic etiology of autoimmunity." (PMID 36980846, 2023). "Germline deletion of Ctla4 resulted in severe autoimmunity with lethality, which prompted researchers to delineate the effects of Ctla4 on T cells and Treg cells separately." (PMID 37197667, 2023). "CTLA-4 inhibits T cell activation, which helps maintain immune homeostasis and prevent autoimmunity." (PMID 37370565, 2023). "This is exemplified by CTLA4 haploinsufficiency, a Mendelian syndrome of T-cell hyperactivation and autoimmunity that often results in paradoxical and unexplained hypogammaglobulinemia and reduced B cells." (PMID 37161048, 2023). "The CTLA‐4 and PD‐1 pathways are critical regulators of T‐cell immunity in the settings of autoimmunity and cancer immunotherapy." (PMID 36727298, 2023). "Systemic injection of Treg-cell-targeting antibodies can result in toxicity, including serious autoimmunity in Treg-targeted cancer immunotherapies that involve CTLA-4 blockade (32, –34)." (PMID 37253006, 2023). "Mechanistically, T cells are equipped with several cell surface inhibitory receptors, such as cytotoxic T lymphocyte-associated protein-4 (CTLA4) and program cell death receptor-1 (PD-1), which signal T-cell apoptosis as a means to avoid autoimmunity." (PMID 37205112, 2023). "With other molecular targets, such as CTLA-4, the approaches to treatment of cancer vs. autoimmunity are opposite, agonistic vs. antagonistic." (PMID 36275816, 2022). "CTLA-4 is a critical regulator of T-cell homeostasis and self-tolerance and represents a key inhibitor of autoimmunity." (PMID 35893056, 2022). "It is not known through which mechanisms the immunosuppressive function of Treg cells is enhanced by CTLA-4, though Treg cell-specific blockade or knockout of CTLA-4 considerably impedes their ability to control both antitumor immunity and autoimmunity." (PMID 35145371, 2022). "Patients with homozygous or compound heterozygous variants in LRBA gene and heterozygous variants in CTLA-4 gene fail to express CTLA-4 protein on surface and have been reported to develop CVID phenotype with autoimmunity, lymphoproliferation and inflammation." (PMID 35795667, 2022). "Antibodies targeting CTLA-4 or PD-1 and its ligands ensure the enhancement of immune reactions against malignant cells, while also promoting autoimmunity." (PMID 36204105, 2022). "Immune checkpoints, represented by programmed cell death-1 (PD-1) and cytotoxic T-lymphocyte-associated protein-4 (CTLA-4), are inhibitory regulators in the immune system, facilitating the maintenance of peripheral tolerance and preventing autoimmunity." (PMID 35494073, 2022). "Due to its dampening effect, CTLA-4 is a critical regulator of T-cell homeostasis and self-tolerance and represents a key inhibitor of autoimmunity." (PMID 35893056, 2022). "Evidence from clinical studies shows that CTLA4-based autoimmunity is involved in the maintenance of chronic inflammation in the peritoneal environment, with pre-clinical evidence of anti-CTLA antibodies as a potential novel target therapy for endometriosis." (PMID 36142815, 2022). "CTLA-4 defective expression and downregulation in LRBA-deficient patients was suggested to cause autoimmunity in this group of patients." (PMID 35453810, 2022). "Data from clinical studies show that CTLA4-based autoimmunity is involved in the maintenance of chronic inflammation in the peritoneal environment, with pre-clinical evidence of anti-CTLA antibodies as a potential novel target therapy for endometriosis." (PMID 36142815, 2022). "In comparison, anti-CTLA4 agents seemed to affect the function of the posterior pituitary only through the extension of inflammation/autoimmunity reactions primarily triggered in the anterior pituitary (panhypophysitis)." (PMID 35205804, 2022).
Autoimmunity (continued). "While this CTLA4 SNP suggests an involvement of enhanced autoimmunity in DCM, their follow-up of disease course was 1-year post-diagnosis, in which it did not appear to have an influence." (PMID 36263134, 2022). "This systematic review provides a summary of the available pieces of evidence about CTLA4-based autoimmunity in the pathogenesis of endometriosis and related infertility." (PMID 36142815, 2022). "Another critical regulatory component is the immune checkpoints, such as CTLA-4 and PD-1, which are less expressed by immune cells in autoimmunity and highly expressed by immune cells and tumor cells in cancers." (PMID 36482486, 2022). "To address the issue of autoimmunity in the child, we have tested the ability of the proband’s PBMCs to be activated and upregulate CTLA-4 expression on T-cells surface." (PMID 35453810, 2022). "CTLA4, predominantly found in intracellular vesicles in FoxP3+ T regulatory cells or activated conventional T cells, is a key regulator of autoimmunity and acts as an immune checkpoint." (PMID 36061211, 2022). "CTLA-4 is well established as a key checkpoint that controls T cell activation and genetic defects lead to lymphoproliferation and profound autoimmunity in both humans and mice." (PMID 36119113, 2022). "The immune checkpoints, programmed cell death protein 1 (PD-1) and Cytotoxic T-lymphocyte-associated protein 4 (CTLA-4), both act to negatively regulate the immune system and are key facilitators of immune homeostasis and prevention of autoimmunity." (PMID 36466910, 2022). "Genetic defects in CTLA-4 function lead to profound and sometimes fatal autoimmunity, which is dependent on ligand-driven CD28 activity." (PMID 36119113, 2022). "B cells can also be activated and differentiate into autoantibody-producing plasma cells, triggering autoimmunity, particularly in patients who receive a combination of CTLA-4 and PD-1 blockade." (PMID 36844924, 2022). "Among CIDs, the highest incidence of autoimmunity is described in patients with autoimmune polyendocrine syndrome 1, LRBA, and CTLA-4 deficiency, and in patients with STAT-related disorders." (PMID 34682853, 2021). "CTLA-4 is primarily expressed by regulatory T cells (Tregs) and has a vital role in self-antigen tolerance and inhibition of autoimmunity." (PMID 34442365, 2021). "The CTLA-4 deficit leads to stimulation of CD28 and its ligands CD80 and CD86, and this causes autoimmunity." (PMID 34948375, 2021). "Studies reported that changes in CTLA-4 are associated with AIH, and a total deficit in mice leads to fatal autoimmunity with liver lymphocytic infiltrate." (PMID 34948375, 2021). "Studies on experimental mice reported that a CTLA-4 deficit can lead to immune dysregulation and autoimmunity." (PMID 34948375, 2021). "If Tregs use OX40 or CTLA-4 to suppress autoimmunity and induce T cell disappearance, the two molecules bind the ligands, OX40L or CD80/86, respectively, before Dsg3H1-Rag2−/− T cell disappearance." (PMID 34848535, 2021). "The types of IEI related to IBD are consistent with genetic defects underlying IEI that are known to be associated with autoimmunity: CGD, X-linked proliferative disease, IPEX, CTLA4 deficiency, and CVID." (PMID 34456911, 2021). "This is an important finding, since CTLA-4 (CD152) is an inhibitory cell-surface molecule that plays an important role in the promotion of anergy, immune regulation, and the prevention of autoimmunity." (PMID 34867947, 2021). "CTLA‐4 is an essential regulatory protein involved in control of T‐cell immune responses and prevention of autoimmunity." (PMID 33960403, 2021). "Here, we evaluated the effect of CTLA-4 and PD-L1 expression in regulating T-cell tolerance and autoimmunity in RR-MS patients to uncover the possible relationship of these immune checkpoints in the pathogenesis of RR-MS." (PMID 34442365, 2021).
Autoimmunity (continued). "This is also in line with severe autoimmunity and lymphoproliferative disorder observed in CTLA-4 gene deletion mice compared to moderate autoimmunity, including aplastic anemia, glomerulonephritis, and arthritis, seen in PD-1-deficient mice." (PMID 33692958, 2021). "Conversely, CD28 antagonists designed as CTLA-4-Ig fusion proteins are effective at ameliorating symptoms in autoimmune disorders and at preventing transplant rejection." (PMID 32665635, 2020). "Specifically, CTLA4 acts as a brake on the immune system, so less CTLA4 means less of a brake and therefore possibly more autoimmunity." (PMID 32835228, 2020). "Given the promising results of CD28 and CTLA4 blockade in small animal models, strategies to target this pathway were developed in several clinical trials for the treatment of autoimmunity." (PMID 33251233, 2020). "Immune checkpoints (IC) proteins, such as cytotoxic T-lymphocyte-associated antigen 4 (CTLA-4), programmed death 1 (PD-1) and PD-L1, are immune system regulators that maintain homeostasis and prevent autoimmunity in physiological conditions." (PMID 32276524, 2020). "CTLA-4 is a critical negative regulator of T cell responses, and the action of CTLA4 on Treg cells can control the activity of other cells and controlling fatal autoimmunity." (PMID 32278632, 2020). "Experiments in knockout mice have demonstrated the important role that CTLA4 plays in protection against autoimmunity." (PMID 32278632, 2020). "Treg cell-specific genetic ablation of CTLA4 or blockade with anti-CTLA-4 antibody significantly compromise their ability to regulate both autoimmunity and antitumor immune response." (PMID 31340499, 2019). "Initially established for cancer therapy (checkpoint blockade), mimicking checkpoints such as CTLA4 (CTLA4-Ig, abatacept, belatacept) is used as treatment for autoimmunity." (PMID 30740105, 2019). "The normal Treg count and CTLA-4 expression maintain adequate Treg suppression to prevent autoimmune disorders." (PMID 31921117, 2019). "LRBA (lipopolysaccharide-responsive beige-like anchor) and CTLA-4 (cytotoxic T-lymphocyte-associated protein 4) deficiencies are two closely related protein deficiencies that were detected in patients with CVID and autoimmunity." (PMID 31921101, 2019). "As an immune checkpoint, CTLA-4 has been used as a therapeutic target in both autoimmunity and malignancy." (PMID 31156616, 2019). "In conclusion, our work identifies a role for DEF6 in regulating CTLA-4 availability and trafficking to prevent autoimmunity, in line with CTLA-4 functioning both as immune rheostat and defining thresholds of immune activation for anti-cancer immunity." (PMID 31308374, 2019). "In the case of CTLA-4 neutralizing antibodies, autoimmunity including colitis, dermatitis, and hepatitis, has occurred, whereas CTLA-4-Ig treatment resulted in a higher incidence of respiratory infections." (PMID 31061392, 2019). "Ctla4−/− mice are viable, although they develop fatal autoimmunity early in life whereas their Ctla4+/- littermates are healthy." (PMID 31308374, 2019). "In patients with CTLA4 deficiency the frequency of CD4+ Treg cells was normal or slightly decreased, suggesting that autoimmunity in these patients is caused by defective Treg function." (PMID 30443250, 2018). "Programmed cell death protein 1 knock out mice show reduced peripheral tolerance and display autoimmunity, with a milder phenotype compared with CTLA-4 knock out mice." (PMID 30158932, 2018). "CTLA-4 is a co-receptor on T-cells that controls peripheral tolerance and the development of autoimmunity." (PMID 30542345, 2018). "The positive regulatory co-receptors CD28 and inducible co-stimulator (ICOS) transduce stimulatory co-signals, whereas the negative regulatory co-stimulators CTLA-4 and PD-1 are critical for the regulation of peripheral tolerance and autoimmunity." (PMID 28770269, 2018).
Autoimmunity (continued). "Deficiency of the N-glycan branching enzyme Mgat5 in mice promotes T cell activity, endocytosis of CTLA-4 and autoimmunity, including a spontaneous multiple sclerosis (MS)-like disease." (PMID 29487346, 2018). "The loss of CTLA-4 results in removal of CTLA-4 competition with CD28 for B7-1 and B7-2 and is implicated in autoimmunity and cancer." (PMID 29701673, 2018). "CTLA-4 and PD-1 inhibitors are the most clinically successful checkpoint inhibitors nevertheless, there are a number of concerns including autoimmunity, unique adverse effects and toxicity related to checkpoint blockade mAbs." (PMID 28866656, 2018). "Inhibitory receptors, such as PD-1 and CTLA-4, are important checkpoint molecules that prevent autoimmunity under physiological conditions." (PMID 30214445, 2018). "The story with adult CTLA4 depletion is contentious, with studies showing mild to quite severe autoimmunity in mice." (PMID 28646041, 2017). "The role of CTLA-4 in immune suppression and tolerance has been validated in autoimmune mouse models such as type I diabetes and multiple sclerosis, where CTLA-4 blockade results in increased severity of the inflammatory phenotype." (PMID 28073373, 2017). "The CTLA-4 receptor is located on the surface of effector T lymphocytes and interacts with CD80/CD86 (B7-1 or B7-2) on CTLA-4 antigen-presenting cells to induce T cell rest, preventing overactivation of the T cell system in autoimmunity." (PMID 28977985, 2017). "CTLA4 serves as a critical checkpoint inhibitor as it downregulates T cell activation to prevent autoimmunity and allow tolerance to self-antigens." (PMID 28720148, 2017). "While the asymptomatic parents carry either the CTLA-4 mutation or the JAK3 variant, their son has inherited both heterozygous mutations and suffers from hypogammaglobulinemia combined with autoimmunity and lymphoid hyperplasia." (PMID 29375547, 2017). "It is thought that blocking this CTLA-4:B7 interaction with ipilimumab, therefore, can potentiate Th17 mediated autoimmunity." (PMID 27660709, 2016). "The inhibitory CTLA-4 molecule is a crucial regulator of immune responses and a target for therapeutic intervention in both autoimmunity and cancer." (PMID 27487771, 2016). "Mice with Tregs that lack CTLA-4 protein expression were shown recently to develop lethal autoimmunity, revealing that Treg expression of CTLA-4 was necessary for immune suppression and prevention of in vivo autoimmunity." (PMID 27118383, 2016). "The importance of CTLA-4 in regulating autoimmunity was demonstrated early on in CTLA-4 knockout mice, in which CD4-predominant lymphoproliferation develops and results in T cell infiltration of multiple organs and early mortality at 3–4 weeks." (PMID 28031819, 2016). "Within a few weeks, CTLA-4-/- mice die from massive, spontaneous, lethal autoimmunity due to unchecked lymphoproliferation." (PMID 28031817, 2016). "In contrast to CTLA-4, the major role of PD-1 is to limit the activity of T cells in peripheral tissues at the time of an inflammatory response to infection and to limit autoimmunity." (PMID 25823653, 2015). "This is based on an association reported between the development of autoimmunity and favorable antitumor effects for several forms of immunotherapy including IFN-α2b, Interleukin (IL)-2 and anti-CTLA4 blocking antibodies among patients with melanoma." (PMID 26192408, 2015). "Serious AEs of autoimmunity have been reported in recent trials with the checkpoint inhibitors ipilimumab (anti-CTLA-4 monoclonal antibody) and nivolimumab (anti-PD1 monoclonal antibody), and also rarely for other cancer vaccines." (PMID 26082837, 2015). "CTLA4/Fc has been used successfully in animal models of autoimmunity and transplantation and has been approved by the Food and Drug Administration for clinical use." (PMID 24959590, 2014). "Twenty five percent of responders experienced Grade 3/4 autoimmunity attributable to anti-CTLA-4 therapy." (PMID 24594636, 2014).
Autoimmunity (continued). "The reverse stop-signal model can potentially explain how CTLA-4 regulates the activation threshold of T-cells, anergy, autoimmunity, tissue infiltration, and various T-cell effector functions." (PMID 24605322, 2014). "The demonstration that loss of CTLA-4 in the Treg compartment is sufficient to precipitate lethal autoimmunity implies that CTLA-4 is of fundamental importance in the Treg lineage." (PMID 23849743, 2013). "Their therapeutic relevance is highlighted by the increasing use of anti-CTLA-4 antibody in tumor therapy and the development of Treg cell transfer strategies for use in autoimmunity and transplantation settings." (PMID 23849743, 2013). "Ipilimumab is a first-in-class monoclonal antibody against cytotoxic T lymphocyte antigen-4 (CTLA-4), a molecule that prevents unwanted autoimmunity and establishes tolerance to self-antigens by downregulating T-cell activation via a homeostatic feedback loop." (PMID 23340652, 2013). "The co-inhibitory receptor Cytotoxic T-Lymphocyte Antigen 4 (CTLA-4) attenuates immune responses and prevent autoimmunity, however, tumors exploit this pathway to evade the host T-cell response." (PMID 21559358, 2011). "CTLA-4 is a crucial functional molecule in Treg-mediated immunological tolerance, as evidenced by the fact that Treg-specific deletion of CTLA-4 causes aberrant T cell activation and autoimmunity." (PMID 41357215, 2025). "While the control of autoimmunity, either partial or complete, is achieved especially in patients with LRBA/CTLA4 deficiency, IPEX syndrome, and CD25 deficiency, they were also referred to the transplant unit for donor search initiation and fund generation for transplant." (PMID 41142805, 2025). "Additionally, genetic deficiencies in CTLA-4 or its trafficking regulator LRBA result in profound immune dysregulation, autoimmunity, and increased susceptibility to malignancy, which further underscores the checkpoint’s essential regulatory role." (PMID 40723175, 2025). "Indeed, CTLA4 carriers display highly heterogeneous clinical manifestations with a phenotypic spectrum ranging from asymptomatic carrier status to fatal autoimmunity." (PMID 40149457, 2025). "The authors hypothesize that CD80 is critical in maintaining immune tolerance through its interaction with the inhibitory receptor CTLA-4, which functions to modulate the immune response and prevent autoimmunity." (PMID 40725864, 2025). "Indeed, genetic deletion of CTLA-4 results in lymphoproliferation, multiorgan autoimmunity and early death in mice." (PMID 38318190, 2024). "It is noteworthy to mention that the loss of CTLA-4 inhibition in murine models leads to fatal disease soon after birth, in contrast to PD-1–knockout mice that develop nonlethal autoimmunity." (PMID 38226621, 2024). "Among these pathways, the CTLA-4 pathway is considered the main immunosuppressive axis in the body and serves as a crucial therapeutic target for enhancing anti-tumor immunity or inhibiting autoimmunity." (PMID 39314521, 2024). "TCR affinity is a critical factor also for tissue-specific Treg cell function during autoimmunity; indeed, it has been observed that high expression of Treg-associated markers, such as T-bet, GITR, CTLA-4, and ICOS, was strongly correlated with TCR signal strength." (PMID 38432631, 2024). "Studies have shown that genetic defects in CTLA-4 lead to CD28-mediated severe autoimmunity." (PMID 38695984, 2024). "They summarized that endometriosis development is not primarily connected with CTLA4-linked autoimmunity." (PMID 38892453, 2024). "Moreover, evidence from clinical studies revealed that CTLA4-based autoimmunity is related to the maintenance of chronic inflammation in the peritoneal environment, probably resulting from endometriosis-related peritoneal fluid." (PMID 36765791, 2023).